JAK2 (Janus kinase 2)
Diseases named in the same sentence as JAK2 in open-access papers (continued):
Sharing a sentence is not in itself a finding about the gene and the disease.
iron deficiency (6 papers, 2018 to 2024). "Given that JAK2 p.V617F-positive diseases cause myeloproliferation and PV is associated with iron deficiency secondary to erythropoiesis, we selected parameters that identified either of the two phenomena." (PMID 33420222, 2021). "We found that in patients with JAK2 mutation, hepcidin levels were significantly lower, similar to patients with iron deficiency." (PMID 30761871, 2019). "JAK2 mutated patients exhibit iron-restricted erythropoiesis, with lower MCVs and higher sTfR1; systemic iron deficiency, with decreased serum iron, ferritin, and transferrin saturation; and expected lower serum Epo concentration relative to patients with wild-type JAK2." (PMID 30042411, 2018). "Serum iron (22 μg/dL [normal range, 60–160 μg/dL]) and ferritin (5 ng/mL [normal range, 15–200 ng/mL]) were suggestive of iron deficiency, serum erythropoietin was 8 mU/mL (normal range, 4.0–18.5 mU/mL), and a Janus kinase 2 (JAK2) mutation analysis was positive for JAK2V617F." (PMID 30564468, 2018).
kidney damage (6 papers, 2019 to 2025). "Furthermore, activation of the JAK2/STAT3 pathway has been implicated in uric acid-induced kidney damage and the overproduction of inflammatory cytokines." (PMID 40170729, 2025). "We further applied scRNA‐seq to elucidate the therapeutic mechanism of BL23 acupuncture in HUA‐induced nephropathy and explored the potential association of this alteration with NLRP3 inflammasome and JAK2/STAT3 signaling pathways." (PMID 41278550, 2025). "The results showed that EDA inhibited the expression of p-JAK2, p-STAT3 and p-STAT1, accompanied by downregulation of the expression of Bax and caspase-3, and significantly ameliorated kidney damage caused by ischemia–reperfusion injury (IRI)." (PMID 32620154, 2020). "Above all, scRNA‐seq analysis demonstrated that EA exerts anti‐inflammatory effects and reduces the IL‐1β expression in treating HUA‐induced nephropathy through downregulation of both the NLRP3 inflammasome and the JAK2/STAT3 signaling pathway." (PMID 41278550, 2025).
memory impairment (6 papers, 2021 to 2025). "In conclusion, this is a novel pathway accounting for pathological dysfunction in AD, such as amyloid- and age-dependent inactivation of the JAK2/STAT3 axis in the hippocampal neurons causing memory impairment related to AD by disturbing cholinergic neurotransmission." (PMID 36614305, 2023). "Several studies, based on animal research, have suggested that the inhibition of the JAK2/STAT pathway contributes to memory impairment." (PMID 40143170, 2025). "Previous studies have shown that Aβ-dependent inactivation of JAK2/STAT3 axis in hippocampal neurons causes cholinergic dysfunction through presynaptic and postsynaptic mechanisms, leading to AD-related memory impairment." (PMID 39546459, 2024). "It is noteworthy that therapeutic effects of GZFL on memory impairment are depended on the inhibition of neuroinflammatory responses by the blockage of JAK2/STAT3 signaling pathway." (PMID 37465679, 2023). "Amyloid β (Aβ)-dependent inactivation of the JAK2/STAT3 axis in hippocampal neurons has been reported to cause cholinergic dysfunction through presynaptic and postsynaptic mechanisms, leading to AD-associated memory impairment." (PMID 39546459, 2024). "Importantly, inactivated JAK2/STAT1 due to GJ-4 was found to improve memory impairment in focal CI/reperfusion in rats." (PMID 35508616, 2022). "Blocking the JAK2/STAT3 axis in hippocampal neurons leads to cholinergic dysfunction, which results in memory impairments in patients with neurodegenerative diseases." (PMID 33833662, 2021).
pancreatic ductal adenocarcinoma (6 papers, 2020 to 2026). An infiltrating adenocarcinoma that arises from the epithelial cells of the pancreas. "It is an essential factor involved in the STAT 3/JAK2 pathway related to the inflammatory status of pancreatic ductal adenocarcinoma." (PMID 39712504, 2024). "For example, circARFGEF2 sponged miR-1205 and promoted the activation of JAK2, which phosphorylated STAT3 to trigger pancreatic ductal adenocarcinoma lymphangiogenesis and lymph node metastasis." (PMID 38641828, 2024).
pancreatitis (6 papers, 2019 to 2026). Inflammation of the pancreas. "Notwithstanding, we are still in the dark about the mechanism of the SOCS5/JAK2/STAT3 pathway in lung damage elicited by pancreatitis." (PMID 36333771, 2022). "Therefore, a probe into the JAK2/STAT3 pathway mediated by SOCS5 helps us better understand the exact mechanism of lung damage elicited by pancreatitis." (PMID 36333771, 2022). "Interestingly, hydrostatin-SN10 cramps the IL-6-triggered activation of the JAK2/STAT3 pathway, lessens cell apoptosis, inflammation, and oxidative stress and mitigates lung damage induced by pancreatitis." (PMID 36333771, 2022).
paroxysmal nocturnal hemoglobinuria (6 papers, 2023 to 2025). Paroxysmal nocturnal hemoglobinuria (PNH) is an acquired clonal hematopoietic stem cell disorder characterized by corpuscular hemolytic anemia, bone marrow failure and frequent thrombotic events. "In myeloproliferative neoplasms (MPNs) and paroxysmal nocturnal hemoglobinuria (PNH), clonal mutations (e.g., JAK2 V617F) or GPI-anchor deficiencies promote thrombo-inflammation." (PMID 40507729, 2025).
sarcoma (6 papers, 2012 to 2024). A usually aggressive malignant neoplasm of the soft tissue or bone. "To visualize the aggregation process we analyzed GFP-Jak2-transfected Jak2-deficient human sarcoma γ2A (Jak2−/−) cells with a fluorescence microscope." (PMID 23166650, 2012). "LFU combined with PTX significantly induced cell apoptosis, and blocked the cell cycle of sarcoma cells in G2/M phase, and furthermore, inhibited the activation of JAK2/STAT3 signaling pathway." (PMID 36582521, 2022). "After JAK2/STAT3 inhibition, we observed a decrease in c-MYC protein expression in sarcoma cells treated with LFU and PTX combination in vitro." (PMID 36582521, 2022).
Thromboembolism (6 papers, 2016 to 2025). The formation of a blood clot inside a blood vessel that subsequently travels through the blood stream from the site where it formed to another location in the body, generally leading to vascular occlusion at the distant site. "Ruxolitinib is a JAK1/JAK2 inhibitor that has been proposed as an alternative treatment in HU‐intolerant or resistant PV patients with lower thromboembolism risk." (PMID 40781888, 2025). "The association of JAK2 mutation with thromboembolism is well established in the literature." (PMID 32164591, 2020).
acute megakaryoblastic leukemia (5 papers, 2010 to 2024). Acute megakaryoblastic leukemia (AMKL) is a form of acute myeloid leukemia (AML) that occurs predominantly in childhood and particularly in children with Down syndrome (DS-AMKL). "Another point mutation first identified in a megakaryoblastic cell line derived from an acute megakaryoblastic leukemia (AMKL) patient, and subsequently detected in a screen of human AMKL cell lines for STAT5 activation, presented a T875N substitution in the kinase domain of JAK2." (PMID 20585391, 2010).
aneurysm (5 papers, 2023 to 2026). Bulging or ballooning in an area of an artery secondary to arterial wall weakening. "Taken together, this opens up discussion for potential influences of the JAK2 V617F variant on the aneurysmal disease processes in the thoracic aorta, possibly through modulation of vascular smooth muscle cell function or response to mechanical stress." (PMID 39062663, 2024). "While JAK2 mutations may contribute to a pro-inflammatory and pro-thrombotic environment, which could theoretically influence vascular integrity, direct evidence of their role in aneurysm formation is still limited." (PMID 40135024, 2025). "JAK2 V617F may contribute a meaningful proportion of otherwise unexplained aneurysm patients." (PMID 39062663, 2024). "Moreover, as the downstream targets of JAK2, phosphorylation of signal transducer and activator of transcription 3 and 1 (p-STAT1 and p-STAT3) were also significantly higher in fusiform aneurysms compared with the normal cerebral arteries." (PMID 38741091, 2024).
Burkitt lymphoma (5 papers, 2021 to 2024). A rare form of malignant mature B-cell non-Hodgkin lymphoma. "The selective JAK2 inhibitor TG101209 induced cell differentiation, apoptosis, and G2/M cell cycle arrest in Raji and Ramos Burkitt lymphoma cells by downregulation of MYB upon inhibition of JAK2/STAT3 signaling." (PMID 38835346, 2024). "Constitutive activation of JAK2/STAT3 is a major oncogenic signaling event involved in the development of Burkitt lymphoma (BL)." (PMID 34588425, 2021). "Janus kinase 2 (JAK2) mediates Burkitt lymphoma growth by phosphorylating TOPK at Y74." (PMID 37016377, 2023). "In the present study, we investigated the antilymphoma activity of TG101209, a specific JAK2 inhibitor, on EBV-positive and EBV-negative Burkitt lymphoma cell lines and primary BL cells." (PMID 34588425, 2021). "In the present study, we chose TG101209, a more specific or selective JAK2 kinase inhibitor (at approximately 30-fold greater selectivity for JAK2 than JAK3), as an exploration of anti-Burkitt lymphoma activity." (PMID 34588425, 2021). "In brief, we showed for the first time that TG101209, a specific JAK2 inhibitor, could inhibit Burkitt lymphoma growth, induce cycle arrest, differentiation and apoptosis of BL cells, and prolong the survival of Ramos cell-bearing mice by inhibiting the JAK2/STAT3/c-MYB signaling axis." (PMID 34588425, 2021).
cholangiocarcinoma (5 papers, 2019 to 2023). A carcinoma that arises from the intrahepatic biliary tree (intrahepatic cholangiocarcinoma) or from the junction, or adjacent to the junction, of the right and left hepatic ducts (hilar cholangiocarcinoma). "Second, by using L1000, we queried gene signatures from ALDH-high cholangiocarcinoma cells and identified JAK2 inhibitor as a potential candidate." (PMID 34440089, 2021). "Third, one of the commercial JAK2 inhibitors, ruxolitinib, was found to significantly inhibit cholangiocarcinoma cell migration." (PMID 34440089, 2021). "Cryptotanshinone, a natural active compound of S. miltiorrhiza Bunge, has been shown to affect cell cycle arrest and apoptosis through the PI3K/Akt/NFκB and JAK2/STAT3 pathways in cholangiocarcinoma cells." (PMID 31406500, 2019). "Collectively, our studies suggest that ruxolitinib might suppress the ALDH1A3 activation through the JAK2/STAT1/3 pathway in cholangiocarcinoma, and trials should be undertaken to evaluate its efficacy in clinical therapy." (PMID 34440089, 2021). "In this study, we chose a listed JAK2 inhibitor, ruxolitinib, which inhibits ALDH1A3 expression in vitro and cholangiocarcinoma cell migration." (PMID 34440089, 2021). "In conclusion, by using the LINCS program, we discovered that a JAK2 inhibitor, ruxolitinib, can downregulate ALDH1A3 expression and inhibit cell proliferation and migration in cholangiocarcinoma cell lines." (PMID 34440089, 2021). "We also used ALDH1A3-high and ALDH1A3-low populations of cholangiocarcinoma cell lines from the library of integrated network-based cellular signatures (LINCS) program and assessed the effects of ruxolitinib, a commercially available JAK2 inhibitor." (PMID 34440089, 2021). "To explore how ruxolitinib, a JAK2 inhibitor, reduces ALDH1A3 expression in cholangiocarcinoma cells, we used a microarray to investigate the transcription factors that fluctuate the most when applying different ruxolitinib concentrations to a cholangiocarcinoma cell line." (PMID 34440089, 2021).
classical Hodgkin lymphoma (5 papers, 2013 to 2025). "Classical Hodgkin Lymphoma (cHL) represents a striking example, as amplification of the 9p24.1 chromosomal region, harboring PD-L1, PD-L2, and JAK2, is a hallmark of the disease." (PMID 41425548, 2025). "In classical Hodgkin lymphoma (cHL) and mediastinal large B-cell lymphoma, the extended PD-1 ligand/9p24.1 amplification region contains the Janus kinase 2 (JAK2) locus." (PMID 27974689, 2017).
clear cell renal cell carcinoma (5 papers, 2022 to 2025). "Previously we reported that IL4Rα and IL13Rα1 (Type II receptor) is a prognostic marker and involved in the development of clear cell renal cell carcinoma (ccRCC) through JAK2/FOXO3 pathway." (PMID 35207737, 2022). "Similarly, the cycle regulator CyclinD1 was maintained as a target gene of the JAK2/STAT3 signaling pathway subjected to the regulation of PBX1 in clear cell renal carcinoma." (PMID 36361531, 2022). "(2022) demonstrated that IL-1RII can also promote oncogenic signaling by activating the Janus kinase 2 (JAK2)/signal transducer and activator of transcription 3 (STAT3) pathway in clear cell renal cell carcinoma (ccRCC)." (PMID 41211420, 2025). "For example, constitutive activation of JAK2/STAT3 signaling has been reported to contribute to tumor growth and metastasis in clear cell renal cell carcinoma, gallbladder cancer, and other malignancies, highlighting its role as a potential therapeutic target." (PMID 40586636, 2025).
cutaneous melanoma (5 papers, 2018 to 2022). A primary melanoma arising from atypical melanocytes in the skin. "The second example is a selective JAK1 and JAK2 inhibitor ruxolitinib and the skin melanoma cell line A375 with a GRmax value of − 0.25." (PMID 36434556, 2022). "Another study revealed that JAK2 was a prognostic biomarker in skin cutaneous melanoma and was involved in gene regulation." (PMID 33083484, 2020). "JAK1, JAK2 and STAT3 genotypes and alleles in 248 cutaneous melanoma patients and 274 controls." (PMID 35982955, 2022). "JAK1, JAK2, and STAT3 significant combined genotypes in 248 cutaneous melanoma patients and 274 controls." (PMID 35982955, 2022). "Many of them were previously appreciated in the genome of skin melanomas (e.g., MITF, NOTCH2, PD-L1 and JAK2 amplifications, or CDKN2A deletions); however, the CNAs in genomic locations harboring PAX5, ETS1, BCL7, RAD51, APAF1, FOXO3 and CTNNA1 are novel." (PMID 33779796, 2021). "JAK1, JAK2, and STAT3 haplotypes in 248 cutaneous melanoma patients and 274 controls." (PMID 35982955, 2022).
cyst (5 papers, 2018 to 2024). A sac-like closed membranous structure that may be empty or contain fluid or amorphous material. "It was shown that JAK2 expression strongly increases in ADPKD and JAK2 blockade reduces cyst growth." (PMID 38671465, 2024). "JAK2 is a key kinase that most likely contributes to cyst growth by activating STAT as a transcription factor." (PMID 38671465, 2024). "To study the ability of the JAK2/STAT3 pathway to drive cystogenesis we performed cystogenesis assays in vitro using a monoculture grown in three dimensions (3D cyst assays)." (PMID 30872773, 2019). "To find out how curcumin blocks STAT3 activity we studied JAK2, which is highly expressed by cyst-lining cells in vivo and is known to activate STAT3 by phosphorylation." (PMID 30872773, 2019). "Contrarily, both Jak2 and Jak3 mRNA levels increased in a time-dependent manner during cyst breakdown and the establishment of the primordial follicle pool." (PMID 29242197, 2018). "Inhibition of either JAK2 or JAK3 prevents germline cyst breakdown and primordial follicle formation." (PMID 29242197, 2018). "Pkd1nl/nl murine models revealed heterotopic JAK2 expression in cyst-lining cells and interstitium and validated that JAK2 inhibition could postpone cystic growth in ADPKD." (PMID 37208335, 2023). "By contrast, in kidneys of mice with ADPKD, JAK2 is higher in cyst-lining cells when compared to normal tubules and critically, it is ectopically expressed in the interstitium, suggesting that ectopic JAK2 may contribute to ADPKD." (PMID 30872773, 2019). "Hence, JAK2 expression is temporally and spatially coincident with cyst growth in the Pkd1nl/nl mouse model of ADPKD." (PMID 30872773, 2019). "Therefore, JAK2 may participate in cyst breakdown and primordial follicle formation by regulating germ cell loss during mouse ovarian development." (PMID 29242197, 2018).
gallbladder cancer (5 papers, 2021 to 2025). "In this study, we investigate the cytotoxic effect of AZD1480 that is a JAK2 inhibitor in SNU308 human gallbladder cancer cells." (PMID 35207737, 2022). "We showed that AZD1480 induced apoptosis via regulation of JAK2/FOXO3 pathway in human gallbladder cancer SNU308 cells." (PMID 35207737, 2022). "We demonstrated that the downregulated IL4Rα or IL13Rα1 caused apoptosis in SNU308 gallbladder cells and investigated the anti-carcinogenic effect of AZD1480, a JAK2 inhibitor, in human gallbladder carcinoma SNU308 cells." (PMID 35207737, 2022). "AG490, JAK2 inhibitor, also inhibited the proliferation and invasion of gallbladder cancer cells through inhibition of JAK2/STAT3 signaling pathway." (PMID 33917914, 2021). "Additionally, it has been recently linked to gallbladder cancer metastasis through the GPRC5A, JAK2 (Janus kinase 2), STAT3 (signal transducer and activator of transcription 3), and TNS4 (tensin 4) signalling pathways." (PMID 40427604, 2025). "However, the effect of AZD1480, a JAK2 inhibitor, in human gallbladder cancer has hardly been investigated." (PMID 35207737, 2022). "Therefore, in this study, we tried to investigate the involvement of JAK2/FOXO3 pathway as one of down-stream signaling pathway in gallbladder cancer cells." (PMID 35207737, 2022). "Therefore, our findings suggests that the IL4Rα and IL13Rα1 complex and JAK2 signaling pathway could be efficient therapeutic targets for gallbladder cancer treatment." (PMID 35207737, 2022). "Leptin and its receptor LEPR promote the proliferation and metastasis of gallbladder carcinoma, which may participate in the regulation of MMPs and the VEGF family through the SOCS3/JAK2/STAT3 pathways." (PMID 33397392, 2021).